NAMPT (nicotinamide phosphoribosyltransferase)
Diseases named in the same sentence as NAMPT in open-access papers (continued):
Sharing a sentence is not in itself a finding about the gene and the disease.
psoriasis (21 papers, 2010 to 2025). An autoimmune condition characterized by red, well-delineated plaques with silvery scales that are usually on the extensor surfaces and scalp. "The study found increased NAD+ levels in the lesional skin of psoriasis patients, which is associated with high levels of NAMPT—an enzyme involved in NAD+ synthesis." (PMID 40650250, 2025). "In conclusion, our results showed that NAMPT-mediated NAD salvage pathway contributes to psoriasis pathogenic processes by amplifying epithelial auto-inflammatory responses in psoriasis." (PMID 34202251, 2021). "Pharmacological inhibition of NADPH oxidases/NAMPT/PARP/AIFM1 axis decreased the expression of pathology-associated genes in human organotypic 3D skin models of psoriasis." (PMID 34748530, 2021). "Interestingly, NAMPT has been associated with different inflammatory conditions, including psoriasis (PS), another chronic inflammatory skin disease." (PMID 37175698, 2023). "Visfatin (NAMPT), elafin, and chemerin are promising candidates for both diagnostic applications and as therapeutic targets in immune-mediated, genetic, environmentally influenced, and inflammatory skin diseases such as psoriasis, primarily due to their dual pro- and anti-inflammatory properties." (PMID 40650250, 2025). "In summary, the visfatin/NAMPT-mediated NAD+ salvage pathway plays a significant role in the development of psoriasis by intensifying the auto-inflammatory responses within the epithelial cells." (PMID 41002974, 2025). "In several disorders, including arthritis and psoriasis, the NAMPT‐mediated NAD+ salvage pathway is thought to have inflammatory function, indicating that the NAD+ salvage pathway is associated with inflammation." (PMID 39739648, 2025). "Consistently, in publicly available clinical datasets of psoriasis, we also observed significant upregulation of NAMPT and PARP genes in skin samples, with a notable correlation between their expressions." (PMID 39203802, 2024). "In our study, bioinformatics analysis of sequencing data revealed significant upregulation of NAMPT and PARPs in activated DCs and psoriasis patient samples." (PMID 39203802, 2024). "It has been reported in the literature that NAMPT is overexpressed in peripheral blood mononuclear cell (PBMC) of psoriasis patients, but it has returned to normal during the cure period." (PMID 39513038, 2024). "Analysis of clinical psoriasis databases further indicated a positive correlation between NAMPT overexpression and DCs hyperactivation, consistent with our observation that reduced NAM levels contribute to heightened DCs activation." (PMID 39203802, 2024). "Increased expression of NAMPT has been observed in skin samples from patients with psoriasis compared with healthy subjects." (PMID 37445960, 2023). "In the same line, reduction of NAMPT-derived NAD+ via pharmacological inhibition of NAMPT reduced the pathological changes in psoriasis and atopic dermatitis and diminished the expression of pro-inflammatory biomarkers." (PMID 37513811, 2023). "Immunohistochemical analysis of samples from healthy skin and psoriasis lesions showed that NAMPT was hardly detected in healthy epidermis and dermis." (PMID 34748530, 2021). "Other than in epithelial compartment, NAMPT expression is also enhanced in peripheral blood mononuclear cells of patients with severe psoriasis, indicating its involvement in systemic inflammation mediated by circulating immune cells." (PMID 34202251, 2021). "Further investigations will be needed to ascertain the potential involvement of NAD+-sirtuin-1-dependent pathway via C/EBPα/π in the regulation of NAMPT expression in psoriasis." (PMID 34202251, 2021). "NAMPT was increased in several inflammatory conditions including rheumatoid arthritis, inflammatory bowel disease and psoriasis; moreover, inhibition of NAMPT is beneficial in some preclinical animal models." (PMID 34895340, 2021).
psoriasis (continued). "Of note, we found that NAMPT expression is strongly reduced by Secukinumab, an anti-IL-17A antibody successfully used in the treatment of psoriasis patients, suggesting its implication in disease pathogenesis." (PMID 34202251, 2021). "The potential anti-inflammatory effects of intracellular NAMPT inhibitors and/or neutralizing NAMPT antibodies will be further investigated in experimental murine models of psoriasis." (PMID 34202251, 2021). "In conclusion, this study proposes that NAMPT-mediated NAD salvage pathway contributes to psoriasis pathogenesis by amplifying epithelial auto-inflammatory responses in psoriasis." (PMID 34202251, 2021). "Consistent with this, clinical data support the alteration of NAD+ and PAR metabolism in psoriasis, pointing to NAMPT, PARP1, and AIFM1 as novel therapeutic targets to treat skin inflammatory disorders." (PMID 34748530, 2021). "Enhancement of NAMPT expression was also observed in inflammatory bowel diseases as well as in psoriasis." (PMID 29546048, 2018). "Summary of the studies on NAMPT (visfatin) role in psoriasis." (PMID 40650250, 2025). "Secondly, the increase in NAD+ levels due to visfatin/NAMPT activity works in conjunction with psoriasis-related cytokines to enhance the production of inflammatory chemokines, which are essential for attracting neutrophils and Th1/Th17 cells to the affected area." (PMID 41002974, 2025). "Collectively, these findings indicate that NAMPT could be a promising target for suppressing activated DCs in psoriasis and that the NAMPT-PARP axis serves as a predictive biomarker for severe psoriasis." (PMID 39203802, 2024). "Indeed, NAMPT gene expression was previously found upregulated in PBMCs from patients with severe psoriasis." (PMID 39409176, 2024). "Notably, clinical data analysis consistently revealed a significant correlation between NAMPT expression and DCs infiltration in psoriasis patient samples." (PMID 39203802, 2024). "Parthanatos has also been involved in human psoriasis in which PARP1 is overactivated downstream of the NAD+ generating enzyme nicotinamide phosphoribosyltransferase (NAMPT) and the translocation of AIF from mitochondria to nuclei can be observed in skin lesions." (PMID 36743979, 2023). "In addition, microarray and real-time polymerase chain reaction (PCR) analyses have shown an overexpression of NAMPT in peripheral blood mononuclear cells of patients with psoriasis." (PMID 37445960, 2023). "NAMPT overexpression is thought to contribute mainly to the pathogenesis of psoriasis by exacerbating an autoinflammatory loop, leading to an increased production of cytokines and chemokines by keratinocytes and promoting the recruitment of inflammatory cells from the blood." (PMID 37445960, 2023). "Similarly, inhibition of NAMPT, PARP, and AIFM1 reduced the transcript levels DEFB4 and S100A8, another inflammation marker associated with psoriasis, while all treatments further reduced LOR and FLR mRNA levels, as did all-trans retinoic acid (ATRA)." (PMID 34748530, 2021). "However, NAMPT was widely overexpressed in the spinous layer and in a few basal keratinocytes and dermal cells in psoriasis lesional skin." (PMID 34748530, 2021). "Our results lead to identify the NAMPT-mediated NAD salvage pathway as the key metabolic pathway involved in the accumulation of intracellular NAD in psoriatic skin lesions, and to confer to it a pathogenic role in psoriasis skin." (PMID 34202251, 2021). "NAMPT, the rate-limiting step enzyme in the NAD+ salvage pathway, has been associated with oxidative stress and inflammation, being identified as a universal biomarker of chronic inflammation, including psoriasis." (PMID 34748530, 2021). "NAMPT/visfatin, a potent mediator of inflammation, was increased in several autoimmune diseases, such as, rheumatoid arthritis, systemic lupus erythematosus, ulcerative colitis, Crohn’s disease, and psoriasis." (PMID 26767650, 2016).
psoriasis (continued). "Notably, phosphoribosyl transferase (NAMPT) and PARPs are significantly upregulated in lipopolysaccharide (LPS)-stimulated DCs and psoriasis patients; elevated NAMPT and PARPs expression in psoriasis patients correlates with higher psoriasis area and severity index (PASI) scores." (PMID 39203802, 2024). "In addition, NAMPT level was found to be elevated in many autoimmune diseases, that is, rheumatoid arthritis, systemic lupus erythematosus, inflammatory bowel diseases, and psoriasis." (PMID 26884761, 2016). "An abnormal increase in visfatin/NAMPT and poly(ADP-ribose) (PAR) polymerase (PARP) activity, along with the nuclear translocation of AIFM1, was observed in lesional skin from psoriasis patients." (PMID 41002974, 2025). "The PPI results and friends analysis demonstrated strong correlations between S100A9, S100A8, NAMPT, TYMP and others, suggesting their potential involvement in the regulation of PANoptosis in psoriasis." (PMID 39480805, 2024). "Based on the analysis of publicly available clinical databases, we observed a close link between the NAMPT-PARP axis and psoriasis, which provides a new predictor for PASI score in psoriasis." (PMID 39203802, 2024). "To further explore the relationship between DCs activation and the NAMPT-PARP axis in clinical samples, we reanalyzed a publicly accessible transcriptomic dataset of skin tissues from psoriasis patients (GEO: GSE121212)." (PMID 39203802, 2024). "The results obtained in zebrafish prompted us to study the impact of inhibition of oxidative stress, NAMPT and PARP1, in organotypic 3D human psoriasis models." (PMID 34748530, 2021). "The mRNA levels NAMPT were upregulated, while those of NMNAT3 were down-regulated in psoriasis lesional skin." (PMID 34748530, 2021). "Consistently, an aberrant induction of NAMPT and PARP activity, together with AIFM1 nuclear translocation, was observed in lesional skin from psoriasis patients." (PMID 34748530, 2021). "Comparing gene expression in skin samples of normal and psoriasis patients (lesions and non-lesions), NAMPT overexpression appeared in lesions skin." (PMID 39513038, 2024). "Since NAM impairs DCs function by inhibiting PARPs activation and considering the significant correlation between NAMPT and PARPs, we examined whether the NAMPT-PARP axis correlated with the PASI score in psoriasis patients." (PMID 39203802, 2024). "A study of chronic skin inflammation reveals that hyperactivation of PARP1 in response to ROS-induced DNA damage, fueled by NAMPT-derived NAD+, mediates skin inflammation via parthanatos cell death, identifying NAMPT, PARP1 and AIFM1 as novel therapeutic targets for psoriasis." (PMID 34748530, 2021). "Taken together, our data further confirm the microarray expression profile results, thus suggesting that the abnormal upregulation of NAMPT in psoriatic lesions, due at least in part to the inflammatory cytokine milieu and NAD metabolism itself, contributes to psoriasis pathogenesis." (PMID 34202251, 2021). "Furthermore, NAMPT was identified as a potential biomarker capable of differentiating lesional from non-lesional skin in patients with psoriasis." (PMID 40650250, 2025). "Furthermore, the aberrant induction of NAMPT and PARP activity was observed in the lesional skin of psoriasis patients, supporting the role of these signaling pathways in psoriasis and pointing to NAMPT and PARP1 as potential novel therapeutic targets in treating skin inflammatory disorders." (PMID 37175698, 2023). "Since NAMPT/visfatin/PBEF is elevated in several autoimmune diseases (e.g., rheumatoid arthritis, inflammatory bowel disease, psoriasis, and systemic lupus erythematosus), we hypothesized that it might be potentially involved in the inflammatory cascade in Graves' orbitopathy." (PMID 29546048, 2018).
psoriasis (continued). "The expression of NAMPT which is a pre-B cell-enhancing factor is increased in colonic biopsy specimens of IBD patients compared to healthy controls, it is also up-regulated in plasma and synovial fluid of RA patients; and in PBMC of psoriasis in the diseased stage." (PMID 20444268, 2010). "In addition, BIRC5, NAMPT and BCL2 may affect the development of psoriasis by regulating autophagy." (PMID 38129460, 2023).
Insulin resistance (20 papers, 2011 to 2025). Increased resistance towards insulin, that is, diminished effectiveness of insulin in reducing blood glucose levels. "Visfatin, also known as NAMPT, has been previously associated with insulin resistance, visceral adiposity, and systemic inflammation." (PMID 41301714, 2025). "Sirtuin 1 (Sirt1) and nicotinamide phosphoribosyltransferase (Nampt) are the rhythmically expressed genes closely associated with insulin resistance." (PMID 32334629, 2020). "NAMPT has been suggested association with atherosclerosis and insulin resistance." (PMID 27229177, 2016). "Added to this is nicotinamide phosphoribosyltransferase (NAMPT), regulator of the response to oxidative stress, apoptosis, lipid and carbohydrate metabolism, inflammation and insulin resistance." (PMID 39744134, 2024). "For 842 patients, pre-therapy associations were HCV RNA, homeostatic model assessment for insulin resistance (HOMA-IR) index, and body mass index with eNAMPT levels, and NAMPT-rs61330082 T allele with total cholesterol levels." (PMID 33446046, 2021). "As a circadian upstream factor of SIRT1, NAMPT is involved in insulin resistance through PPARγ and adiponectin." (PMID 32334629, 2020). "Furthermore, adipose-specific NAMPT is closely related to insulin resistance in the adipose tissue, liver, and skeletal muscle through the regulation of PPARγ and adiponectin." (PMID 32334629, 2020). "In addition to the influence of NAMPT on lipid metabolism, we also found that FK866 markedly reduced Akt phosphorylation, indicating that NAMPT also improve insulin resistance in NAFLD through promoting insulin signaling in hepatocytes." (PMID 28449683, 2017). "Therefore, it is currently unclear if NAMPT is involved in the development of insulin resistance (IR) or atherosclerosis." (PMID 27229177, 2016). "Interestingly, the stress axis affecting compounds dexamethasone and isoproterenol, that are known to induce insulin resistance in adipocytes induced NAMPT transcription." (PMID 21687707, 2011). "Moreover, miR-34a has been shown to be strongly related to insulin resistance development, and elevated miR-34a suppresses nicotinamide phosphoribosyl transferase (NAMPT), resulting in reduced NAD + biosynthesis in the liver of obese mice fed with high-fat diet." (PMID 37808009, 2023). "Mice with a adipocyte-specific deletion of NAMPT exhibit lower NAD+ levels in their fat tissues, suffer from multi-organ insulin resistance and have impaired adipose tissue function." (PMID 38364095, 2024). "Hyperandrogenism resulted in the negative regulation of BMAL1-induced expression of the NAMPT/NAD+/SIRT1 pathway, which further suppressed GLUT4, leading to insulin resistance in the liver and adipose tissues of rats." (PMID 32334629, 2020). "Based on the arrhythmic Nampt and Sirt1 mRNA expressions in the liver and adipose of PCOS-like rats, we speculated that NAMPT and SIRT1 might be the bridge linking BMAL1 and insulin resistance in PCOS patients." (PMID 32334629, 2020). "Meanwhile, hyperandrogenism led to the negative regulation of BMAL1-induced expression of NAMPT/NAD+/SIRT1 pathway, further inhibiting downstream GLUT4 and contributing to insulin resistance in mature adipose cells, which was consistent with our previous results in HepG2 cells." (PMID 32334629, 2020).
prostate carcinoma (17 papers, 2014 to 2026). A carcinoma that arises from epithelial cells of the prostate gland. "In conclusion, we identify the YAP/NNMT axis as a determinant of innate sensitivity to NAMPT inhibition in prostate cancer." (PMID 41608637, 2026). "NAMPT is also involved in oxidative stress response as knockdown NAMPT sensitizes prostate cancer cells to H2O2 by regulating the expression of anti-oxidant genes catalase (CAT) and manganese superoxide dismutase (SOD)." (PMID 31598701, 2019). "Expression of NAMPT is elevated in prostate cancer tissues, and inhibition of NAMPT, through shRNA-mediated knockdown or small molecules, impairs proliferation of prostate cancer cell lines." (PMID 30258629, 2018). "NAD+ likely plays a critical role in tumorigenesis, as depletion of intracellular NAD+ levels by inhibition of NAMPT can impair prostate cancer cell proliferation, a result that we reproduced in our study." (PMID 30258629, 2018). "It had been previously shown that NAMPT-knockdown sensitized prostate cancer cells to etoposide and paclitaxel." (PMID 29156703, 2017). "Targeting the YAP/NNMT/NAMPT axis may represent a novel strategy for treating stem-like/mesenchymal, therapy-resistant prostate cancers." (PMID 41608637, 2026). "Interestingly, while expression of CD38 is lost in advanced prostate cancers, the expression of NAMPT is increased." (PMID 35677882, 2022). "Additionally, de novo lipogenesis required the involvement of NAMPT in prostate cancer cells." (PMID 40303304, 2025). "SIRT1 is also found over-expressed in many cancers and frequently NAMPT is concurrently over-expressed with SIRT1, which is important for prostate cancer cell survival and stress response." (PMID 25146220, 2014). "In addition, NAMPT inhibitors potentiated the efficacy of the radionuclide 177Lu-DOTATATE in neuroendocrine tumors, and sensitized head and neck cancer and prostate cancer models to radiotherapy." (PMID 34068917, 2021). "In addition, NAMPT is prominently overexpressed along with SIRT1 in human prostate cancer cells and SIRT1 is a key downstream target of NAMPT for prostate cancer cell growth and survival." (PMID 26389889, 2015).